TUSC2 (tumor suppressor 2, mitochondrial calcium regulator)
Description:
May function as a tumor suppressor, inhibiting colony formation, causing G1 arrest and ultimately inducing apoptosis in homozygous 3p21.3 120-kb region-deficient cells.
Synonyms: C3orf11; FUS1; PDAP2; PAP
Tractability: PROTAC: its protein half-life has been measured.
Gene: Protein-coding gene on chromosome 3 (50,320,027 to 50,328,251, reverse strand). Ensembl gene ENSG00000114383.
Subcellular location (Human Protein Atlas): Cytosol; Vesicles
Gene Ontology:
Molecular function: protein binding
Biological process: inflammatory response; regulation of mitochondrial membrane potential
Cellular component: mitochondrion
Genetic constraint (gnomAD): Loss-of-function variants: 7 observed, 9.56 expected, observed/expected ratio (o/e) 0.73, 90% interval 0.41 to 1.37. That is too few expected variants to judge how well the gene tolerates losing a copy. Missense variants: 132 observed, 127.26 expected, observed/expected ratio (o/e) 1.04, 90% interval 0.9 to 1.2. Synonymous variants: 61 observed, 51.1 expected, observed/expected ratio (o/e) 1.19, 90% interval 0.97 to 1.48.
Homologues: Orthologues: chimpanzee TUSC2 (99% identical), macaque TUSC2 (99% identical), dog TUSC2 (95% identical), guinea pig TUSC2 (93% identical), mouse Tusc2 (93% identical), zebrafish tusc2a (71% identical), tropical clawed frog tusc2 (67% identical), zebrafish tusc2b (67% identical), rat Tusc2l1 (50% identical), Caenorhabditis elegans C09E9.1 (38% identical).
Diseases named in the same sentence as TUSC2 in open-access papers:
TUSC2 is named in the same sentence as 44 diseases in open-access papers, as found by Europe PMC text mining. Sharing a sentence is not in itself a finding about the gene and the disease. The quoted sentences say what the papers report.
lung carcinoma (25 papers, 2009 to 2025). "Since its initial discovery in lung cancer, TUSC2 loss has also been reported in glioma, sarcoma, and cancers of the breast, ovaries, and thyroid." (PMID 37173921, 2023). "TUSC2 encodes a tumor suppressor 2 protein that is deleted in some carcinomas, including lung cancer." (PMID 36859458, 2023). "TUSC2 is reduced in a significant number of lung cancers, and this reduced expression is associated with worse prognosis." (PMID 32153582, 2020). "Allele losses and genetic alterations of TUSC2 are found in multitudinous cancer types, including lung carcinoma and breast cancer." (PMID 30944041, 2019). "TUSC2 is located on chromosome 3p21.3, a region in which deficient gene expression is observed in lung cancers." (PMID 27661106, 2016). "Expression of the TUSC2/FUS1 tumor suppressor gene in TUSC2 deficient EGFR wildtype lung cancer cells increased sensitivity to erlotinib." (PMID 27845352, 2016). "Tumor suppressor candidate 2 is encoded by the TUSC2 gene which is a highly conserved lung cancer candidate gene." (PMID 23403885, 2013). "TUSC2-defective gene expression is detected in the majority of lung cancers and is associated with worse overall survival." (PMID 24146957, 2013). "Loss of TUSC2 protein expression in lung cancer may be mediated through the 5′ and 3′ untranslated regions (UTR) of the TUSC2 mRNA." (PMID 37173921, 2023). "Moreover, they found unmyristoylated TUSC2 to be more susceptible to proteasomal degradation in lung cancer." (PMID 37173921, 2023). "Interestingly, TUSC2 is infrequently mutated in lung cancer patients, with only 5% of lung cancer cases presenting with a TUSC2 mutation." (PMID 37173921, 2023). "TUSC2 emerges as a pivotal tumor suppressor, with its decreased expression commonly observed in various cancers, including lung cancer, malignant mesothelioma, soft-tissue sarcoma, high-grade human glioma, and thyroid cancer." (PMID 40243558, 2025). "Large-scale analysis of TUSC2 expression in lung cancer and in metaplastic and dysplastic bronchial lesions found significantly lower levels of TUSC2 relative to normal hyperplastic epithelium." (PMID 40428391, 2025). "TUSC2 overexpression in H1299 lung cancer cells significantly decreases colony formation and induces G1 cell cycle arrest." (PMID 37173921, 2023). "Tumor Suppressor Candidate 2 (TUSC2/FUS1) was first discovered as a candidate tumor suppressor gene (TSG) within the 630-kb homozygous deletion on chromosomal region 3p21.3 in lung cancer." (PMID 37173921, 2023). "Restoration of TUSC2 expression in lung cancer cells significantly inhibits tumor cell growth and colony formation and increases the sensitivity of cultured resistant lung cancer cells to the EGFR inhibitor erlotinib." (PMID 37173921, 2023). "MiR-19a, miR-378, miR-93, miR-98, and miR-197 are all highly expressed in lung cancer patient samples and cell lines and promote lung cancer cell survival and growth through the downregulation of TUSC2." (PMID 37173921, 2023). "Rescuing TUSC2 expression through TUSC2 vector-carrying nanoparticles (REQORSA) treatment has demonstrated positive results in lung cancer patients." (PMID 37173921, 2023). "TUSC2 overexpression also sensitized multiple lung cancer cell lines to treatment with the AKT inhibitor MK2206 in vitro and in vivo." (PMID 37173921, 2023). "Since the discovery of TUSC2 as a candidate tumor suppressor frequently lost in lung cancer, TUSC2 has been found to be lost in many other cancer types, which further supports TUSC2 as an important tumor suppressor." (PMID 37173921, 2023). "Conversely, unmyristoylated TUSC2 had significantly reduced tumor suppressive function, resulting in reduced TUSC2 mediated apoptosis and cell cycle inhibition in lung cancer." (PMID 37173921, 2023). "Overall, TUSC2 is an established tumor suppressor frequently lost in lung cancer patients and has promising anti-tumor effects in both in vitro and in vivo studies." (PMID 37173921, 2023).
lung carcinoma (continued). "TUSC2 was first discovered as a candidate tumor suppressor gene that is located on a frequently deleted region of chromosome 3p21.3 in lung cancer." (PMID 37173921, 2023). "An analysis of TUSC2 expression showed the efficient distribution of TUSC2 in the tumor, demonstrating the potent tumor-suppressive activity of TUSC2 in primary and disseminated human lung cancer." (PMID 35326434, 2022). "Other miRNAs suppressing FUS1/TUSC2 mRNA expression include miR-663 in ovarian cancer, miR-19a in lung cancer, miR-378 in mesenchymal stem cells, and miR-584 in thyroid cancer." (PMID 35181743, 2022). "Deng and colleagues reported that forced expression of TUSC2 enhanced the antitumour activity of cisplatin in human lung cancer cells; TUSC2 restoration sensitized lung cancer cells to treatment with EGFR inhibitors." (PMID 31973107, 2020). "The oncogenic activities of miR-93, miR-98 and miR-197 in lung cancer are mediated by the silencing of TUSC2." (PMID 31973107, 2020). "Lung cancer cell lines H157 and H1299 with doxycycline dose response inducible TUSC2 expression were developed using the Tet-On system." (PMID 27845352, 2016). "Microarray mRNA expression analysis of TUSC2 inducible lung cancer cells treated with erlotinib uncovered defects in the response to oxidative stress suggesting that increasing reactive oxygen species (ROS) would enhance therapeutic efficacy." (PMID 27845352, 2016). "We previously showed that exogenous expression of TUSC2 induced apoptosis in lung cancer cell lines and inhibited lung tumor xenograft growth and metastasis in mouse models." (PMID 26053020, 2015). "TUSC2 maps to the human chromosome 3p21.3 region, which is frequently lost or reduced in lung cancer." (PMID 26367773, 2015). "This study provides the molecular rationale and biomarker profile for combining TUSC2 gene therapy with kinase inhibitors for more effective treatment of lung cancer." (PMID 24146957, 2013). "TUSC2 is often deleted in lung, breast, head and neck, renal and other types of cancer and was reported to be methylated in human lung cancer cells." (PMID 23403885, 2013). "Tumor suppressor gene TUSC2/FUS1 (TUSC2) is frequently inactivated early in lung cancer development." (PMID 22558101, 2012). "Preclinical studies in human lung cancer cell lines identified the intrinsic apoptosis pathway as a mediator of cell death following forced expression of TUSC2." (PMID 22558101, 2012). "The tumor suppressor property of TUSC2 was confirmed experimentally on lung cancer cell lines in vitro and on xenograft mice in vivo." (PMID 19852844, 2009). "TUSC2 is a novel tumor suppressor from the critical 3p21.3 chromosomal region frequently deleted in multiple cancers that plays a critical role in lung cancer development." (PMID 19852844, 2009). "We used specific anti-TUSC2 antibodies successfully tested previously on a set of human lung cancer samples." (PMID 19852844, 2009). "While clinical trial on restoration of TUSC2 activities in lung cancer patients is underway, its status and role in mesothelioma, an aggressive thoracic inflammatory cancer associated with exposure to asbestos, had never been established." (PMID 19852844, 2009). "Additionally, multiple key elements were found within the 3′ UTR that lead to altered TUSC2 mRNA regulation in lung cancer, resulting in reduced TUSC2 protein expression." (PMID 37173921, 2023). "Interestingly, TUSC2 directly interacts with and inhibits the activity of c-Abl tyrosine kinase, which provides an alternative mechanism of TUSC2-mediated suppression of lung cancer." (PMID 37173921, 2023).
lung carcinoma (continued). "One potential mechanism for TUSC2-mediated tumor suppression in lung cancer may occur through TUSC2 regulation of the epidermal growth factor receptor (EGFR) pathway." (PMID 37173921, 2023). "In addition to being found in lung cancers, chromosome 3p abnormalities frequently occur in breast cancer patients, specifically within region 3p21.3, and suggests that TUSC2 is frequently lost in breast cancer." (PMID 37173921, 2023). "In addition to miRNA-mediated TUSC2 downregulation, TUSC2 N-terminal myristoylation also regulates TUSC2 protein expression in lung cancer." (PMID 37173921, 2023). "Multiple studies have demonstrated that TUSC2 is highly tumor suppressive in lung cancer." (PMID 37173921, 2023). "FUS1/TUSC2 (FUSion1/TUmor Suppressor Candidate 2) is a tumor suppressor gene (TSG) originally described as a member of the TSG cluster from human 3p21.3 chromosomal region frequently deleted in lung cancer." (PMID 35181743, 2022). "Indeed, forced induction of TUSC2 expression in lung cancer cells increased NK cell infiltration and stimulated NK cell activation." (PMID 32153582, 2020). "Taken together, these findings show that TUSC2 can decrease PD-L1 expression in lung cancer cells." (PMID 29296193, 2017). "Study of TUSC2-modified lung cancer cells may reveal novel vulnerabilities targetable by existing immunotherapies." (PMID 29296193, 2017). "This ability to modify the tumor microenvironment suggests that TUSC2 could be added to checkpoint inhibitors to improve the treatment of lung cancer." (PMID 29296193, 2017). "Expression of the tumor suppressor gene TUSC2 is reduced or absent in most lung cancers and is associated with worse overall survival." (PMID 26053020, 2015). "TUSC2-erlotinib cooperativity in vitro could be reproduced in vivo in subcutaneous tumor growth and lung metastasis formation lung cancer xenograft mouse models." (PMID 26053020, 2015). "Our findings provide new insights into the molecular mechanisms of TUSC2-mediated tumor suppression, and suggest that the therapeutic activity of TUSC2 could extend the use of erlotinib to lung cancer patients with wildtype EGFR." (PMID 26053020, 2015). "Interestingly, the patient who had the metabolic response had a lung carcinoma with neuroendocrine features which expressed very low levels of TUSC2 protein." (PMID 22558101, 2012). "The role of TUSC2 as a tumor suppressor in lung cancer is widely accepted." (PMID 19852844, 2009). "The effect of these mutation on TUSC2 function has not been investigated in lung cancer." (PMID 37173921, 2023). "Our results revealed that miR-19a downregulates the target genes FOXP1, TP53INP1, TNFAIP3, and TUSC2 and that these genes might play important roles in the tumorigenesis of lung cancer; however, the invasion inhibition potency was found to differ among the four genes." (PMID 26367773, 2015). "More recently, Li and colleagues reported that the coexpression of the tumour suppressor genes, TUSC2 and LKB1, leads to an inhibition of lung cancer cell growth inducing an arrest of the cell cycle." (PMID 31973107, 2020). "Evidence to date indicates that TUSC2, also known as FUS1, behaves as a tumor suppressor in several types of cancers, including lung cancer, breast cancer and thyroid cancer." (PMID 30944041, 2019). "In lung cancers and various other malignancies, this chromosomal region is frequently deleted and FUS1/TUSC2 expression is often lost." (PMID 25024751, 2014). "In vivo, TUSC2 systemic delivery, by nanoparticle gene transfer, combined with MK2206 treatment markedly inhibited growth of tumors in a human LKB1-defective H322 lung cancer xenograft mouse model." (PMID 24146957, 2013). "Furthermore, large-scale analysis of TUSC2 expression in lung cancer and in bronchial squamous metaplastic and dysplastic lesions showed reduced expression levels of TUSC2 compared to normal hyperplastic epithelia, indicating it could be an early event in cancer progression." (PMID 23403885, 2013).
lung carcinoma (continued). "Although multiple patients did show stable disease, as well as successful upregulation of TUSC2 protein expression in lung cancer biopsies, the majority of the patients had no response." (PMID 37173921, 2023). "Additionally, TUSC2 regulates multiple downstream EGFR targets, such as FGFR2, mTOR, AKT, and c-Abl in lung cancer." (PMID 37173921, 2023). "TUSC2 overexpression significantly increased phosphorylation and enzymatic activity of AMP-activated protein kinase (AMPK), which is necessary for TUSC2-mediated MK2206 sensitivity in lung cancer cells." (PMID 37173921, 2023). "Non-myristoylated TUSC2 displays an impaired ability to impede colony formation in vitro and lung cancer growth in vivo compared to N-terminal myristoylated TUSC2, suggesting that myristoylation of TUSC2 is required, in part, for its tumor suppressor function." (PMID 37173921, 2023). "Tumor suppressor candidate 2 (TUSC2) nanovesicle-based immunogene therapies, when combined with anti-PD-1 therapy, were shown to significantly inhibit tumor growth and extend survival in mouse models of Kras-mutant lung cancer." (PMID 35203256, 2022). "Importantly, TUSC2-expressing nanoparticles have been tested in clinical trials in patients with lung cancer and showed anti-tumor activity and no significant side effects." (PMID 27661106, 2016). "TUSC2 protein is reduced or absent in over 80% of lung cancers." (PMID 26053020, 2015). "In addition, we used a xenograft mouse model of the human lung cancer cell line H322, which is LKB1-defective, to determine whether TUSC2 systemic nanovesicle-based gene delivery and MK2206 treatment would effectively inhibit xenograft tumor growth." (PMID 24146957, 2013). "However, myristoylated and non-myristoylated TUSC2 are detected in lung cancer samples." (PMID 37173921, 2023).
non-small cell lung carcinoma (10 papers, 2012 to 2023). A group of at least three distinct histological types of lung cancer, including non-small cell squamous cell carcinoma, adenocarcinoma, and large cell carcinoma. "Loss or reduction of TUSC2 has been reported in non-small cell lung carcinomas (NSCLC), in small cell lung carcinomas, in mesothelioma, in oesophageal carcinoma, in glioblastoma and in sarcomas." (PMID 31973107, 2020). "We reported that TUSC2 restoration in 3p21.3-deficient non-small cell lung cancer (NSCLC) cells suppressed tumor growth by induction of apoptosis and alteration of cell kinetics in vitro and in vivo through Apaf-1." (PMID 26053020, 2015). "Recently, we have demonstrated that exogenous expression of TUSC2 in non-small cell lung carcinoma cells, deficient of its expression, significantly inhibited tumor cell growth." (PMID 24146957, 2013). "TUSC2 sensitizes non-small cell lung cancer cells to AKT inhibitor, MK2206 in LKB1 dependent manner." (PMID 30944041, 2019). "TUSC2 mRNA is constitutively expressed in human non-small cell lung cancer H1299 cells." (PMID 27440378, 2016). "Consequently, TUSC2 gene therapy has been tested in patients with non-small cell lung cancer." (PMID 37173921, 2023). "FUS1/TUSC2 mRNA was detected in lung and sarcoma cancer cell lines and sarcoma tissues, but no protein expression was detected in SCLC or non-small cell lung carcinoma (NSCLC) cells." (PMID 35181743, 2022).